PCDHGA4 (protocadherin gamma subfamily A, 4)
Description:
Potential calcium-dependent cell-adhesion protein. May be involved in the establishment and maintenance of specific neuronal connections in the brain.
Synonyms: PCDH-gamma-A4
Tractability: Antibody: UniProt places it where antibodies can reach, with medium confidence; UniProt predicts a signal peptide or a membrane-spanning region; its Gene Ontology location is reachable by antibodies, with medium confidence.
Gene: Protein-coding gene on chromosome 5 (141,355,021 to 141,512,975, forward strand). Ensembl gene ENSG00000262576.
Subcellular location: Cell membrane
Subcellular location (Human Protein Atlas): Plasma membrane; Vesicles; Cytosol; Nucleoplasm
Gene Ontology:
Molecular function: protein binding; cell adhesion molecule binding; calcium ion binding
Biological process: cell adhesion; homophilic cell-cell adhesion
Cellular component: plasma membrane; membrane
Genetic constraint (gnomAD): Loss-of-function variants: 38 observed, 55.73 expected, observed/expected ratio (o/e) 0.68, 90% interval 0.52 to 0.89. The upper end of that interval is the gene's LOEUF score, 0.89, which puts it in group 3 of 6, group 1 being the genes least tolerant of losing a copy. Missense variants: 1,298 observed, 1,291.6 expected, observed/expected ratio (o/e) 1, 90% interval 0.96 to 1.05. Synonymous variants: 511 observed, 544.56 expected, observed/expected ratio (o/e) 0.94, 90% interval 0.87 to 1.01.
Homologues: Orthologues: rabbit PCDHGA4 (86% identical), chimpanzee PCDHGA4 (86% identical), pig PCDHGA4 (86% identical), mouse Pcdhga4 (82% identical). Paralogues in human: PCDHGA3 (74% identical), PCDHGA5 (74% identical), PCDHGA6 (73% identical), PCDHGA10 (73% identical), PCDHGA7 (73% identical), PCDHGA8 (73% identical), PCDHGA2 (73% identical), PCDHGA12 (72% identical), PCDHGA1 (72% identical), PCDHGA11 (71% identical), PCDHGA9 (71% identical), PCDHGB1 (50% identical), and 49 more.
Diseases named in the same sentence as PCDHGA4 in open-access papers:
PCDHGA4 is named in the same sentence as 3 diseases in open-access papers, as found by Europe PMC text mining. Sharing a sentence is not in itself a finding about the gene and the disease. The quoted sentences say what the papers report.
Obesity (1 paper, 2023). Accumulation of substantial excess body fat. "Along with this, 366 CpG islands were identified for 326 genes that were related to obesity, among which the gene PCDHGA4 (protocadherin γ subfamily A, 4) demonstrated the highest number of target IDs—52 target IDs that were differentially methylated between NW and OW/OB children." (PMID 37239458, 2023).
PCDHGA4 also shares sentences with these, for which no sentence is quoted: septal defects (1 paper); tumor (1).